MIR133A1 (microRNA 133a-1)
Synonyms: hsa-mir-133a-1; MIRN133A1; mir-133a-1
Gene: MicroRNA gene on chromosome 18 (21,825,698 to 21,825,785, reverse strand). Ensembl gene ENSG00000283927.
Gene Ontology:
Biological process: miRNA-mediated post-transcriptional gene silencing
Cellular component: RISC complex
Homologues: Orthologues: chimpanzee ptr-mir-133a-1 (100% identical), macaque mml-mir-133a (100% identical), rabbit MIR133A1 (100% identical), dog MIR133A (99% identical), pig MIR133A1 (99% identical), zebrafish mir133a-1 (97% identical), mouse Mir133a-1 (76% identical), rat Mir3582 (56% identical). Paralogues in human: MIR133A2 (93% identical), MIR133B (64% identical).
Diseases named in the same sentence as MIR133A1 in open-access papers:
MIR133A1 is named in the same sentence as 3 diseases in open-access papers, as found by Europe PMC text mining. Sharing a sentence is not in itself a finding about the gene and the disease. The quoted sentences say what the papers report.
atrial fibrillation (1 paper, 2013). A disorder characterized by an electrocardiographic finding of a supraventricular arrhythmia characterized by the replacement of consistent P waves by rapid oscillations or fibrillatory waves that vary in size, shape and timing and are accompanied by an irregular ventricular response. "We re-sequenced the MIR1-1, MIR1-2, MIR133A1, MIR133A2, and MIR133B genes, that encode the cardiac-enriched miRNAs, miR-1 and miR-133, in 120 individuals with familial atrial fibrillation and identified 10 variants, including a novel 79T > C MIR133A2 substitution." (PMID 23497314, 2013).
prostate tumors (1 paper, 2022). "As a result of the overexpression of TF ESF1, miRNA MIR133A1 is downregulated to upregulate the target gene EGFR, responsible for cell proliferation, local recurrence, and distant-organ metastasis in prostate tumors." (PMID 35164166, 2022).
type 2 diabetes (1 paper, 2024). "A possible trend toward significance was found in the expression of the MIR126 gene (p = 0.051), the MIR133A1 gene (p = 0.076), the MIR143 gene (p = 0.08), and the MIR320A gene (p = 0.095) in patients with type 2 diabetes." (PMID 38256676, 2024). "The value of MIR133A1 gene expression showed a statistical trend toward significance in patients with type 2 diabetes (median: 0.147; mean: 0.233; standard deviation: 1.056) in contrast to patients without type 2 diabetes (median: −0.168; mean: −0.106, standard deviation: 0.883)." (PMID 38256676, 2024).